MRPL13 (mitochondrial ribosomal protein L13)
Diseases named in the same sentence as MRPL13 in open-access papers (continued):
Sharing a sentence is not in itself a finding about the gene and the disease.
cancer (continued). "Our research aims to reveal the function of MRPL13 in multiple cancers in a groundbreaking way through biological information analysis and experimental verification, suggesting the possibility of MRPL13 as a new target to treat cancer." (PMID 37827692, 2023). "Furthermore, the correlation between MRPL13 expression and FOXM1 expression was confirmed in various pan-cancers, which enriches the theoretical framework of MRPL13’s role in promoting the occurrence and progression of pan-cancer." (PMID 37827692, 2023). "Finally, in the analysis of gene expression and dryness score, we found that the expression of MRPL13 was directly proportional to the dryness score of cancer cells in most pan-cancers." (PMID 37827692, 2023). "All of these results indicate that the MRPL13 gene may interact with many genes and play a role in multiple cancers through various pathways, which is an interesting phenomenon that warrants further investigation." (PMID 37827692, 2023). "Crossing the genes related to MRPL13 in each cancer resulted in a gene set of 40 genes and." (PMID 37827692, 2023). "Finally, using Kaplan-Meier survival analysis of the validated dataset in GEO, we confirmed that MRPL13 is a reliable factor for predicting the prognosis of cancer." (PMID 37827692, 2023). "Moreover, MRPL13 in pan-cancer is related to the cancer immune infiltration pattern, methylation level and cuproptosis-related genes." (PMID 37827692, 2023). "Finally, the effect of knocking out MRPL13 on cancer cells was compared by gene silencing experiments." (PMID 37827692, 2023). "The cell cycle ranked fifth, which is consistent with the fact that MRPL13 may promote the growth of cancer cells by affecting the cell cycle." (PMID 37827692, 2023). "Here, we tested MRPL13 expression in normal tissues, various cell lines, and pan-cancer." (PMID 34868337, 2021). "Pan-cancer analysis further revealed the prognostic value of MRPL13 in human cancers." (PMID 34868337, 2021). "In addition, three different databases based on TCGA cohort were used to evaluate the expression of MRPL13 mRNA in 33 cancer types." (PMID 34868337, 2021). "Furthermore, many studies have demonstrated that MRPL13 has a significant role in cancer." (PMID 39859078, 2025). "Another main finding is that in most pan-cancers, including UVM, GBMLGG, SKCM, KICH, and LGG, MRPL13 is positively correlated with most chemokines, receptors, and immune-stimulation and immunosuppression marker genes and negatively correlated with a few pan-cancers, such as ESCA, HNSC, and LUSC." (PMID 37827692, 2023). "However, a thorough examination of MRPL13 across cancers remains uncertain." (PMID 37827692, 2023). "In addition, we also analyzed the correlation of MRPL13 expression with TMB in human cancer." (PMID 34868337, 2021). "High MRPL13 expression was related to advanced stage and poor survival in NSCLC patients, and the silencing of MRPL13 suppressed cancer cell proliferation." (PMID 38987867, 2024). "Therefore, targeting MRPL13 may have unexpected effects on cancer treatment." (PMID 37827692, 2023). "TMB was positively correlated with MRPL13 in six cancers, GBM, LUAD, STES, UCEC, STAD, and DLBC, but negatively correlated with MRPL13 in UVM, COADREAD, COAD, and READ." (PMID 37827692, 2023). "Pan-cancer TMB and overall survival time showed dysregulation of MRPL13 is significantly related to the OS and TMB levels in various cancers." (PMID 34868337, 2021). "Cancer with a positive correlation between TMB and MRPL13 may benefit more from treatment with immune checkpoint inhibitors." (PMID 37827692, 2023). "By comparing cancer and normal tissue data from TCGA, we identified differential expression of MRPL13 in 18 types of cancer, except for cancers lacking comparative data or differences." (PMID 37827692, 2023). "However, there is no obvious correlation between MRPL13 and methylation genes in other types of cancer, for instance UCS, DLBC, LIHC, GBM, and CHOL." (PMID 37827692, 2023).
cancer (continued). "Therefore, MRPL13 may exert a negative influence in regulating the immune response of cancer and act as a potential molecular marker for the benefits of immunotherapy, especially in LUAD." (PMID 37827692, 2023). "Interestingly, the most altered RBP in our analysis, MRPL13, has never been studied in cancer." (PMID 35453681, 2022).
psychiatric disorder (1 paper, 2020). A disorder characterized by behavioral and/or psychological abnormalities, often accompanied by physical symptoms. "Among them SPATS2L, ZEB2, KCHN8, and MRPL13 which have been previously connected to psychiatric disorders with the latter two being responsive to nicotine treatment." (PMID 33004014, 2020).
MRPL13 also shares sentences with these, for which no sentence is quoted: bladder cancer (2 papers); gastric cancer (2); head and neck squamous cell carcinoma (2); ovarian carcinoma (2); colon cancer (1); esophageal cancer (1); esophageal squamous cell carcinoma (1); gastric adenocarcinoma (1); myocardial ischemia (1); ovarian epithelial malignant tumors (1); pancreatic cancer (1); papillary thyroid carcinoma (1); uterine cancer (1).